LMNA (lamin A/C)
Diseases named in the same sentence as LMNA in open-access papers (continued):
Sharing a sentence is not in itself a finding about the gene and the disease.
laminopathies (continued). "In addition, the same LMNA mutations can have different penetrance between individuals, which sometimes translates into lack of symptoms or failure to ascribe them to laminopathies." (PMID 29637811, 2018). "Unfortunately, PI treatment can also impair maturation of LMNA by inhibiting the activity of ZMPSTE24, thus inducing laminopathies in a manner similar to progeroid disorders." (PMID 37731189, 2024). "The Drosophila Lamin C (LamC) gene is an orthologue of human LMNA and has been used to model laminopathies." (PMID 37190051, 2023). "Interestingly, different sets of mutations in the LMNA gene and genes coding for interacting proteins, such as emerin (EMD/STA gene) and BAF (barrier-to-autointegration, BANF1 gene), give rise to a variety of genetic disorders collectively called laminopathies." (PMID 30691039, 2019). "Here we have focused on LMNA mutations with cardiac-predominant phenotype, as opposed to extending HCA to the much larger and broader multisystem laminopathies." (PMID 30402260, 2018). "There is no specific therapy for laminopathies, including DCM- associated with the LMNA mutations." (PMID 35891706, 2022).
Hutchinson-Gilford progeria syndrome (157 papers, 2005 to 2026). "Mutations in LMNA, encoding nuclear lamina protein Lamin A/C, cause premature aging disorders, most notably Hutchinson-Gilford progeria syndrome." (PMID 41632539, 2026). "Mutations in the LMNA (Lamin A/C) cause Hutchinson-Gilford Progeria Syndrome (HGPS), a disorder marked by defective nuclear architecture, impaired muscle development, and severe cardiovascular complications that often lead to premature death." (PMID 41596589, 2026). "More recently, Koblan and colleagues applied the dual-AAV-BE in a mouse model of Hutchinson-Gilford progeria syndrome (HGPS) to correct the C:G-to-T:A mutation in the LMNA gene responsible for the disease." (PMID 41496894, 2026). "A de novo, synonymous, point mutation (1824C>T) in the LMNA gene activates a cryptic 5′ splice site, leading to Hutchinson-Gilford Progeria Syndrome (HGPS), a rare genetic disorder marked by premature aging." (PMID 40568141, 2025). "Hutchinson-Gilford progeria syndrome (HGPS) is a rare genetic disorder caused by LMNA gene mutations and aberrant expression of progerin." (PMID 41209003, 2025). "Hutchinson-Gilford progeria syndrome (HGPS) is a genetic disease caused by a mutation in the LMNA gene, which produces an abnormal nuclear envelope protein called progerin." (PMID 40766643, 2025). "Hutchinson-Gilford progeria syndrome is a premature aging disorder caused by mutations in the LMNA gene, that produce a defective protein called progerin leading to a disorganized nuclear architecture." (PMID 41181393, 2025). "The rare, accelerated aging disease Hutchinson-Gilford Progeria Syndrome (HGPS) is commonly caused by a de novo c.1824 C > T point mutation of the LMNA gene that results in the protein progerin." (PMID 40027545, 2025). "It is known that certain genes analyzed in our study have variants associated with other diseases in addition to MDs; for example, MATR3 is associated with Amyotrophic Lateral Sclerosis 21 and LMNA is associated with Hutchinson-Gilford Progeria Syndrome." (PMID 38755190, 2024). "Mutations in LMNA cause the development of Hutchinson-Gilford syndrome, characterised by early premature ageing." (PMID 36768453, 2023). "Hutchinson-Gilford Progeria Syndrome (HGPS) is premature aging disease caused by the mutation of LMNA (lamin A) gene." (PMID 37198162, 2023). "The mutation of LMNA can lead to pathological states including dilated cardiomyopathy, Hutchinson-Gilford progeria syndrome (HGPS), and atypical progeria syndrome." (PMID 35977926, 2022). "Mutations in lamins, particularly in the LMNA gene, can cause a broad range of diseases such as Hutchinson-Gilford Progeria Syndrome (HGPS), Emery-Dreifuss Muscular Dystrophy, and autosomal dominant leukodystrophy, collectively referred to as laminopathies." (PMID 35721517, 2022). "Mutations in LMNA, which encodes nuclear Lamin A/C, precipitates a premature aging syndrome called Hutchinson-Gilford Progeria (HGPS) that is characterized by the accumulation of protein aggregates." (PMID 32290135, 2020). "Hutchinson-Gilford progeria syndrome (HGPS) is a rare premature aging disease in children caused by an autosomal dominant mutation in the LMNA gene." (PMID 32816594, 2020). "Mutations in LMNA or ZMPSTE24 that prevent prelamin A cleavage cause the severe premature aging disorder Hutchinson-Gilford Progeria syndrome (HGPS) or the related progeroid diseases, mandibuloacral dysplasia type-B (MAD-B) and restrictive dermopathy (RD)." (PMID 33315887, 2020). "Of the 71 patients with AWS, a subset was shown to carry mutations in LMNA, a gene known to be mutated in the Hutchinson-Gilford Progeria syndrome (HGPS), or in POLD1, a DNA polymerase involved in several DNA repair pathways." (PMID 33194896, 2020). "Among progeroid laminopathies, Hutchinson-Gilford Progeria syndrome (HGPS) is a rare premature aging disease caused by mutations in LMNA gene and, in most cases, production of a truncated prelamin A form called progerin." (PMID 30766871, 2019).
Hutchinson-Gilford progeria syndrome (continued). "The second example we chose to highlight here involves the LMNA gene, which is causal of the Hutchinson-Gilford progeria syndrome." (PMID 29228364, 2018). "The typical LMNA mutation responsible for Hutchinson-Gilford progeria results in the expression of a constitutively farnesylated prelamin A pathogenic variant, called progerin." (PMID 29578370, 2018). "The premature aging disease Hutchinson-Gilford syndrome (HGPS) is also caused by defined mutations in the LMNA gene resulting in activation of a cryptic splice donor site leading to a defective truncated prelamin A protein called progerin." (PMID 29702688, 2018). "For example, Hutchinson-Gilford progeria syndrome (HGPS)-associated SNVs in LMNA, a well-known spliced gene, were found within the CS-associated splicing event regions." (PMID 29936497, 2018). "Mutations in LMNA or ZMPSTE24 that impede this prelamin A cleavage step cause the premature aging disease Hutchinson-Gilford progeria syndrome (HGPS), and the related progeroid disorders mandibuloacral dysplasia type B (MAD-B) and restrictive dermopathy (RD)." (PMID 29794150, 2018). "This phenotypic combination was further observed with other LMNA mutations in typical Hutchinson-Gilford progeria or in atypical progeroid syndromes." (PMID 29578370, 2018). "One particularly severe example is Hutchinson-Gilford Progeria Syndrome (HGPS) in which a mutation in the Lamin A/C (LMNA) gene causes premature aging up to seven times faster than normal, usually culminating in death due to cardiovascular complications." (PMID 29149195, 2017). "Mutations in LmnA have been associated with progeria, such as the Hutchinson-Gilford progeria syndrome (HGPS)." (PMID 28797100, 2017). "Hutchinson-Gilford progeria syndrome (HGPS) is a rare genetic condition associated with mutations in the LMNA gene." (PMID 29029393, 2017). "Mutations in the LMNA gene have been described to cause HGPS (Hutchinson-Gilford Progeria Syndrome), an extremely rare genetic disorder that affects 1 in 4–8 million newborns worldwide." (PMID 27409638, 2016). "A heterozygous G608G mutation in the LMNA gene leads to a deletion of 50 amino acids in lamin A protein, termed progerin, and is the predominant cause of Hutchinson-Gilford progeria syndrome (HGPS)." (PMID 24764515, 2013). "Hutchinson-Gilford progeria syndrome is most typically caused by a de novo mutation in the lamin A/C gene (LMNA) that activates a cryptic splice site, producing an abnormal lamin A protein termed progerin." (PMID 24379984, 2013). "For instance, Hutchinson-Gilford progeria syndrome, the classical premature aging syndrome is due to a missense LMNA mutation leading to partially activates a cryptic splice donor site in exon 11, thereby producing an abnormal lamin A protein, progerin." (PMID 23362510, 2012). "The LMNA gene, which encodes the nuclear envelope proteins lamin A and lamin C, has been associated with the progeroid (premature aging-like) syndrome, Hutchinson-Gilford syndrome." (PMID 22279548, 2012). "We and others have recently reported the use of human iPSC platform to model the disease phenotypes and mechanisms of Hutchinson-Gilford progeria syndrome, which is the most severe form of LMNA mutation that leads to premature aging and death." (PMID 23362510, 2012). "Mutations in the LMNA gene have been identified in a number of conditions, including Hutchinson-Gilford progeria syndrome." (PMID 21711540, 2011). "Mutations in LMNA manifest as such varied disorders as muscular dystrophies, lipodystrophies, dermopathies, cardiomyopathies, and progeria syndromes, including Hutchinson-Gilford progeria (HGPS; OMIM ID# 176670)." (PMID 21464947, 2011). "Almost since the discovery that mutations in the LMNA gene, encoding the nuclear structure components lamin A and C, lead to Hutchinson-Gilford progeria syndrome, people have speculated that lamins may have a role in normal aging." (PMID 36260869, 2022).
Hutchinson-Gilford progeria syndrome (continued). "For example, mutations of LMNA gene could result in different isoforms and cause a range of accelerated ageing and peripheral nerve disorders, including Hutchinson-Gilford progeria syndrome and Charcot-Marie-Tooth disease." (PMID 29936497, 2018). "Therefore, releasing any force exerted at the nuclear envelope by the cytoskeleton or chromatin did not rescue nuclear shape, in contrast to what was previously shown in Hutchinson-Gilford progeria due to other LMNA mutations." (PMID 28125586, 2017). "Consistently, PGC-1α expression and ATP production are reduced in fibroblasts derived from Hutchinson-Gilford progeria syndrome, a lethal genetic disease caused by point mutation in LMNA, and both can be rescued by methylene blue, a mitochondrial-targeting antioxidant." (PMID 29736257, 2017). "Similarly, in Hutchinson-Gilford progeria syndrome, a point mutation in exon 11 of the lamin A/C (LMNA) gene causes a silent substitution (GGC→GGT) that results in activation of a cryptic donor splice site." (PMID 17604456, 2007). "For example, the classic Hutchinson-Gilford progeria syndrome (HGPS) is caused by mutations in LMNA encoding for the nuclear lamina proteins lamin A and C1,2." (PMID 39956852, 2025). "A striking example is Hutchinson-Gilford Progeria Syndrome (HGPS), where a mutation in the LMNA gene accelerates aging and drives premature stem cell exhaustion, including MuSC depletion, which results in early-onset muscle degeneration." (PMID 41302153, 2025). "The dissociation of accelerated aging phenotypes and cancer also applies to defects in lamin A/C, e.g. Hutchinson-Gilford progeria syndrome (HGPS) due to mutations in lamin A encoded by LMNA or its protease STE24 encoded by ZMPSTE24." (PMID 38760832, 2024). "Mutations in the LMNA gene have many implications leading to various manifestations of autosomal dominant and recessive conditions such as dilated cardiomyopathy, Emery-Dreifuss muscular dystrophy, congenital muscular dystrophy, Charcot Marie Tooth Disease, and Hutchinson-Gilford progeria syndrome." (PMID 39411178, 2024). "Hutchinson-Gilford progeria syndrome (HGPS) is a rare, autosomal dominant premature aging syndrome caused by mutations in the LMNA gene." (PMID 39110386, 2024). "NGPS shares phenotypic similarities with Hutchinson-Gilford progeria syndrome (HGPS), which has been described in much greater detail and is most often caused by mutation in LMNA that encodes lamin A/C." (PMID 39367234, 2024). "One notorious example is the premature aging disease Hutchinson-Gilford progeria syndrome (HGPS), which is caused by mutations affecting LMNA splicing patterns." (PMID 38926537, 2024). "Insights into the aging process have come from studies of human diseases associated with premature aging as mutations in the lamin A/C gene LMNA cause the Hutchinson-Gilford progeria syndrome (HGPS)." (PMID 37620607, 2023). "Hutchinson-Gilford progeria syndrome (HGPS) is a rare premature ageing disorder caused by a point mutation in the LMNA gene (LMNA c.1824 C > T), resulting in the production of a detrimental protein called progerin." (PMID 35654881, 2022). "Hutchinson-Gilford progeria syndrome (HGPS) is a rare premature aging syndrome, caused by a dominant mutation in LMNA gene." (PMID 35292115, 2022). "Mutations in LMNA, like those found in Hutchinson-Gilford progeria syndrome (HGPS), destabilize lamin A/C-TRF2 interaction, further leading to telomere loss and accelerated cellular aging." (PMID 36589746, 2022). "MB has shown potential for the treatment of Hutchinson-Gilford Progeria Syndrome (HGPS), which is a genetic, premature aging disorder caused by a C to T de novo point mutation on exon 11 of the LMNA gene." (PMID 34943887, 2021). "A study focusing on Hutchinson-Gilford progeria syndrome (HGPS) revealed that a LMNA mutation is up-regulated in the aging process." (PMID 32257547, 2020).
Hutchinson-Gilford progeria syndrome (continued). "LMNA mutations can also cause accelerated aging disorders like Hutchinson-Gilford progeria syndrome (HGPS) and Werner syndrome." (PMID 33316938, 2020). "A rare genetic disorder Hutchinson-Gilford Progeria Syndrome (HGPS) is a premature aging disorder that causes de novo point mutation inside exon 11 of the LMNA gene, leading to the accumulation of progerin." (PMID 33163298, 2020). "Hutchinson-Gilford progeria syndrome (HGPS) is a premature aging disorder, caused by mutation in the gene encoding lamin A/C, which produces a truncated protein called progerin." (PMID 33139753, 2020). "In Hutchinson-Gilford progeria syndrome (HGPS) cells, which are characterized by a mutation in the LMNA gene encoding A-type lamins, residual unrepaired DSBs appear." (PMID 30996128, 2019). "Mutations in LMNA are associated to several diseases, including Hutchinson-Gilford progeria syndrome (HGPS), a premature aging disorder in which individuals present with senile diseases specific to the aging process, as well as dermatosis." (PMID 31269075, 2019). "Mutations in LMNA have been linked to premature aging disorders, including Hutchinson-Gilford progeria syndrome (HGPS)." (PMID 30900948, 2019). "Similar defects in HR also have been observed in Hutchinson-Gilford progeria syndrome (HGPS), which is predominantly caused by a LMNA C1024T mutation." (PMID 29717979, 2018). "The progeroid syndromes caused by LMNA mutations encompass Hutchinson-Gilford progeria syndrome (HGPS), mandibuloacral dysplasia (MAD), Malouf syndrome, and several atypical progeroid syndromes that cannot be assigned clearly." (PMID 30140252, 2018). "One study focused on Hutchinson-Gilford progeria syndrome (HGPS) disease, which is caused by mutation in the LMNA gene." (PMID 28102490, 2017). "Apart from FPLD2, mutations in LMNA gene has been reported to be associated with a wide variety of other disorders including childhood-onset generalized lipodystrophy, muscular dystrophies, neuropathy, hand heart syndrome, mandibuloacral dysplasia, and Hutchinson-Gilford Progeria syndrome." (PMID 27504462, 2016). "Lamins A/C are encoded by LMNA, a single heterozygous mutation of which causes Hutchinson-Gilford progeria syndrome (HGPS)." (PMID 26443848, 2015). "Hutchinson-Gilford Progeria Syndrome (HGPS) is a rare genetic disorder characterized by symptoms that resemble premature aging, and is caused by mutations in the LMNA gene, which encodes lamin A, a key component of the nuclear lamina." (PMID 24363663, 2013). "Hutchinson-Gilford Progeria Syndrome (HGPS) is a rare premature aging disorder caused by a de novo heterozygous point mutation G608G (GGC>GGT) within exon 11 of LMNA gene encoding A-type nuclear lamins." (PMID 20559568, 2010). "Classic Hutchinson-Gilford Progeria syndrome (HGPS) is caused by the mutation c.1824C>T (p.Gly608=) of LMNA, which activates a cryptic splice site in exon 11, producing progerin (lamin A Δ50), a prelamin A variant missing 50 amino acids near the C-terminus and therefore retaining farnesylation." (PMID 41511357, 2026). "Hutchinson-Gilford progeria syndrome (HGPS), which is based on mutations in the LMNA gene and the gene encoding the interacting protein, is one of the most serious diseases in laminopathies." (PMID 38421832, 2024). "Hutchinson-Gilford Progeria Syndrome (HGPS) is an ultra-rare, fatal, premature aging disease caused by an autosomal dominant single base mutation in the lamin A/C (LMNA) gene encoding the nuclear membrane protein lamin A." (PMID 38725831, 2024). "The premature aging Hutchinson-Gilford progeria syndrome (HGPS or Progeria) is characterized by the occurrence of a C-to-T silent mutation (LMNA c.1824 C > T, p.Gly608Gly) in exon 11 of the LMNA gene, encoding for an intermediate filament protein critical for maintenance of the nuclear envelope." (PMID 38132139, 2023).